MAX (MYC associated transcriptional regulator X)
Diseases named in the same sentence as MAX in open-access papers (continued):
Sharing a sentence is not in itself a finding about the gene and the disease.
leukemia (3 papers, 2020 to 2025). A malignant (clonal) hematologic disorder, involving hematopoietic stem cells and characterized by the presence of primitive or atypical myeloid or lymphoid cells in the bone marrow and the blood. "An increased expression of miR-22 in leukemia cells reduces the MAX expression level, blocking cell cycle progression at the G1 phase." (PMID 32102656, 2020). "In the leukemia cell line K562, LTR5_Hs elements are enriched for binding of multiple TFs that control cell cycle and proliferation (e.g., cMYC, MAX, JUND, PU1, and P300), which might reflect the transformed phenotype of these cells." (PMID 33202765, 2020).
melanoma (3 papers, 2017 to 2024). A malignant, usually aggressive tumor composed of atypical, neoplastic melanocytes. "For the first time, we show an interaction between SIRT1 and MYC/MAX/MAD network in melanoma progression, highlighting the SIRT1 role in the regulation of important pathways related to cancer." (PMID 29383100, 2017). "Since Mxd1 is downregulated by SIRT1 in 4C11- and 4C11+ tumor cell lines, we have postulated that MAX could become more available to MYC binding in these melanoma cells." (PMID 29383100, 2017).
multiple endocrine neoplasia (3 papers, 2022 to 2024). Multiple endocrine neoplasia (MEN) is a group of rare inherited cancer syndromes characterized by the development of two or more endocrine gland tumors, sometimes with tumor development in other tissues or organs. "MAX germline mutations may cause new types of multiple endocrine neoplasia." (PMID 39279998, 2024). "Examples of PPGLA mutations include the RET gene in multiple endocrine neoplasia (MEN) syndromes, the VHL gene in von Hippel–Lindau disease, the NF1 gene in Neurofibromatosis type 1, the MAX gene, or the genes of the succinate dehydrogenase complex (SDHB, SDHD, SDHA, SDHC, SDHAF2)." (PMID 36010170, 2022).
neuroendocrine tumors (3 papers, 2020 to 2023). "Despite these studies indicating that MAX may be implicated in neuroendocrine tumors, the role of MAX in PA biological behavior has not been validated." (PMID 37104368, 2023).
Obesity (3 papers, 2015 to 2024). Accumulation of substantial excess body fat. "Similarly, miR-126 had altered expression in obesity and may modulate CCL2 (chemokine ligand 2) through genes that encode ETS1, MAX, NFKB1, RELB, and STAT6 proteins." (PMID 36355127, 2022).
ovarian carcinoma (3 papers, 2013 to 2023). A malignant neoplasm originating from the surface ovarian epithelium. "Mechanistically, MBZ was shown to inhibit multiple cancer-associated signaling pathways including ELK/SRF, NFKB, MYC/MAX, and E2F/DP1 in cisplatin-resistant ovarian cancer cells." (PMID 34232919, 2021). "Mechanistically, MBZ was shown to inhibit multiple cancer-related signal pathways including ELK/SRF, NFKB, MYC/MAX, and E2F/DP1 in cisplatin-resistant ovarian cancer cells." (PMID 34232919, 2021). "Mechanistically, MBZ was revealed to inhibit multiple cancer-related signal pathways including ELK/SRF, NFKB, MYC/MAX, and E2F/DP1 in cisplatin-resistant ovarian cancer cells." (PMID 34232919, 2021). "Similar inhibitory effects by MBZ were observed for the NFKB, MYC/MAX, and E2F/DP1 reporter activities, suggesting that MBZ may exert profound inhibitory effects on cell proliferation pathways in cisplatin-resistant ovarian cancer cells." (PMID 34232919, 2021).
adrenal pheochromocytoma (2 papers, 2015 to 2020). "MAX variants are almost exclusively identified in patients with adrenal pheochromocytoma that are frequently bilateral, while TMEM127 variant carriers most commonly present with single adrenal pheochromocytoma, and occasionally multiple head and neck or thoraco-abdominal PGLs." (PMID 33308260, 2020).
cholangiocarcinoma (2 papers, 2021 to 2023). A carcinoma that arises from the intrahepatic biliary tree (intrahepatic cholangiocarcinoma) or from the junction, or adjacent to the junction, of the right and left hepatic ducts (hilar cholangiocarcinoma). "Our in silico analysis revealed that a total of six TFs (SP1, CREB1, MAX, FHL2, RFX1 and HIF1A) were upregulated in cholangiocarcinoma tissues." (PMID 34199886, 2021). "Moreover, expressions of six TF genes (SP1, CREB1, MAX, FHL2, RFX1, and HIF1A) was positively correlated with the expression of ITGA6 and ITGB1 in cholangiocarcinoma tissues." (PMID 34199886, 2021).
cholestasis (2 papers, 2020 to 2021). Impairment of the bile flow caused by obstruction within the liver, or outside the liver in the bile duct system. "In a mouse model of cholestasis-associated CCA, hypoxia-induced-factor-2α (HIF2α) upregulated miR-210 expression, suppressing MAX network transcriptional repressor (Mnt), which antagonizes cMyc by competing binding to MAX." (PMID 33007962, 2020).
depression (2 papers, 2016 to 2025). "For instance, social defeat induced a depression-like phenotype in male adolescent mice, accompanied by significantly elevated levels of MAX protein in the hippocampus." (PMID 40118833, 2025).
diffuse large B-cell lymphoma (2 papers, 2024). "MYCT1 may represses RUNX1 transcription by binding MAX in diffuse large B-cell lymphoma cells." (PMID 38172714, 2024). "MYCT1 binding to MAX probably suppressed RUNX1 transcription, leading to the inhibition of proliferation and cell cycle of the diffuse large B-cell lymphoma cells." (PMID 38172714, 2024). "Consistent with our results, the study in diffuse large B-cell lymphoma (DLBCL) showed that USP1 directly interacted with and stabilized MAX (a MYC-binding protein) through deubiquitination, then promoted the transcription of MYC target genes." (PMID 39513905, 2024).
hepatic carcinoma (2 papers, 2020 to 2022). "Meanwhile, liver-specific Phb1 knockout (KO) mice develop hepatocellular carcinoma (HCC) spontaneously by regulating MAX, MNT and MATα1." (PMID 36348375, 2022). "Finally, the leiomyosarcoma and hepatic carcinoma of the proband, and her father’s lung adenocarcinoma may be MAX and KIF1B independent." (PMID 33112832, 2020).
liver cancer (2 papers, 2015 to 2024). An epithelial or non-epithelial malignant neoplasm that arises from the liver. "We deduced that the HypoM of MYC and the HyperM of MAX may activate the pathogenesis of arsenic induced liver cancer." (PMID 26046465, 2015).
medulloblastoma (2 papers, 2020 to 2021). A malignant, invasive embryonal neoplasm arising from the cerebellum. "MiR-193a mediated decrease in the expression levels of known targets CCND1, MCL1, and the novel target MAX in the medulloblastoma cells was validated by the western blot analysis." (PMID 32410663, 2020). "MiR-193a not only targeted MAX but several proliferation-related genes like CCND1, E2F1, STMN1, and chromatin modifier gene KMT2A that brought about widespread repression of gene expression in the MYC amplified Group 3 medulloblastoma cells." (PMID 32410663, 2020).
multiple endocrine neoplasia type 2 (2 papers, 2014 to 2016). Multiple endocrine neoplasia type 2 (MEN2) is a multiple endocrine neoplasia, a polyglandular cancer syndrome characterized by the occurrence of medullary thyroid carcinoma (MTC), pheochromocytoma (PCC), in one variant, primary hyperparathyroidism (PHPT). "The kinase signalling subgroup, includes characteristic mutations in REarranged during Transfection (RET) in Multiple Endocrine Neoplasia type 2 (MEN2), Neurofibromatosis type 1 (NF1), transmembrane protein 127 (TMEM127), MYC associated factor X (MAX), EGLN1 (PHD2), KIF1 and IDH1." (PMID 27535829, 2016).
neurofibromatosis (2 papers, 2015 to 2022). A hereditary neoplastic syndrome in which tumors grow in the nervous system. "Two nonsyndromic patients (cases 1 and 2) were negative to germline mutations in genes VHL, SDHB, SDHC, SDHD, SDHAF2, TMEM127, and MAX, while the third case (case 3) had clinical diagnosis of neurofibromatosis syndrome." (PMID 36187102, 2022).
pituitary tumor (2 papers, 2020 to 2022). A benign or malignant neoplasm affecting the pituitary gland. "While loss-of-heterozygosity has not been shown yet, further data are needed to confirm a causal relationship between MAX mutations and pituitary tumors." (PMID 32201880, 2020). "Pituitary tumours thought to be caused by SDHx and MAX variants are indeed rare." (PMID 35938916, 2022). "MAX mutations have been identified in 5 patients with pituitary tumor and pheochromocytoma." (PMID 32201880, 2020).
prostate carcinoma (2 papers, 2017 to 2025). A carcinoma that arises from epithelial cells of the prostate gland. "The increased active nuclear beta-catenin through interaction with MYC/MAX transcription factor functions as a co-repressor of PrKD1 expression and thereby perpetuates the down regulation of PrKD1 in advanced prostate cancer." (PMID 29108267, 2017). "Moreover, addition of MYC/MAX to PrKD1 centered biomarker panel may improve the performance of the panel in discriminating indolent from aggressive prostate cancer." (PMID 29108267, 2017). "While additional studies are needed to prove the feasibility and efficacy of targeting in prostate cancer, it is conceivable that targeting the transcriptional regulators such as MYC/MAX could selectively and indirectly increase the PrKD1 expression in cells." (PMID 29108267, 2017).
renal cell carcinoma (2 papers, 2017 to 2025). "We report a case of MAX-associated renal cell carcinoma and confirm the role of TMEM127 mutations with renal cell carcinoma predisposition." (PMID 28973655, 2017).
sarcoma (2 papers, 2021 to 2025). A usually aggressive malignant neoplasm of the soft tissue or bone. "Notably, several SWIFT domain-interacting TFs represented top dependencies in the cancer cell lines in which interactions were identified such as BPTF and TERF2vin ES cells and YY1 and MAX in U2OS sarcoma cells." (PMID 40766474, 2025).
T cell lymphoma (2 papers, 2020 to 2023). "We also analyzed MYC and MAX mRNA expression levels in other T-cell lymphomas compared with ALCL." (PMID 32587329, 2020). "Subsequently, we detected the expression of USP1, MAX and MYC in DLBCL, Burkitt and T cell lymphoma cell lines by using western blotting analysis, and found that the protein levels of USP1, MAX and MYC were high in RL-4RH cells." (PMID 36352191, 2023). "Taken together, low MAX expression is specific for ALCL among T-cell lymphoma studied, regardless of MYC expression." (PMID 32587329, 2020). "Interestingly, MAX mRNA levels in ALCL were lower than those in other mature T-cell lymphomas, regardless of MYC expression." (PMID 32587329, 2020).
acute myelogenous leukemia (1 paper, 2019). "Since MYC and MAX co-occupy the LCL MTHFD2 promoter and given MYC’s role in MTHFD2 regulation in acute myelogenous leukemia, we investigated a potential role for MYC in EBV induction of MTHFD2 expression." (PMID 31257153, 2019).
adrenal neoplasms (1 paper, 2023). "In this context, increased attention to HIF-MYC/MAX interactions may also provide new therapeutic options for these pediatric adrenal neoplasms." (PMID 37361539, 2023).
Anxiety (1 paper, 2016). Intense feelings of nervousness, tension, or panic often arise in response to interpersonal stresses. "Following social stress episodes and housing in social groups after each defeat, adolescent mice exhibit depressive-like, but not anxiety-like behaviors and show higher MAX nuclear immunoreactivity in hippocampal (HC) but not prefrontal cortical (PFC) neurons." (PMID 27727240, 2016).
Atrophy (1 paper, 2008). Any weakening or degeneration, especially through lack of use. "In this perspective, we think that our approach has given a good contribution: in fact we were able to identify some proteins and transcription factors, such as SMAD3/4, GNB2L1/RACK1, MYC, MAX and JUN whose functions have been studied extensively in tumours and in some atrophy models." (PMID 19108710, 2008). "Furthermore, we studied the enrichment of specific transcription factor (TF) binding sites in the genes relevant for atrophy as revealed by the meta-analysis, obtaining clues for important roles that should be ascribed in the atrophy processes to TF such as SP1, MAX and EEF1D/deltaEF1." (PMID 19108710, 2008).
Barrett's metaplasia (1 paper, 2008). "Quantitative real-time RT–PCR was utilised to assess the expression of the mRNAs encoding c-MYC, MAD1, MXI1, MXI1-0 and MAX in normal epithelia, Barrett's metaplasia and oesophageal adenocarcinoma specimens." (PMID 18493233, 2008). "When expression in adenocarcinoma was evaluated in comparison to matched Barrett's metaplasia it was apparent that expression of MYC, MXI1 and MAX were significantly elevated in the malignant transformation of Barrett's metaplasia." (PMID 18493233, 2008). "Semi-quantitative analysis suggested that MAX expression was significantly higher in adenocarcinoma than in normal mucosae and Barrett's metaplasia." (PMID 18493233, 2008). "Immunohistochemical staining was utilised to establish MYC/MAX/MAD network protein localisation in normal oesophageal and gastric epithelia, Barrett's metaplasia, dysplastic Barrett's epithelium and oesophageal adenocarcinoma." (PMID 18493233, 2008).
bile duct carcinoma (1 paper, 2023). "MAX promotes the growth, migration, invasion, and cell cycle progression of bile duct carcinoma cells." (PMID 37347224, 2023).
brain tumors (1 paper, 2016). "Here we report discovery of a novel recurrent somatic mutation in MAX in brain tumors and study its effects on the development and progression of tumors." (PMID 27294413, 2016).
cervical cancer (1 paper, 2015). A primary or metastatic malignant neoplasm involving the cervix. "From the modules characterized in ES cells, Myc module showed correlation with both E2F/NFY and MAX/CEBP (p < 0.05, χ2-test), suggesting a possible synergy among the individual transcription regulators forming these modules on the regulation of expression of the cervical cancer signature genes." (PMID 26559525, 2015).
chronic lung disease (1 paper, 2019). According to the definitions of the American and British Thoracic Societies, including pulmonary functional tests, X-rays, and CT scans for items such as fibrosis, bronchiectasis, bullae, emphysema, nodular or lymphomatous abnormalities. "Therefore, lifestyles that promote long-term exposure to hypoxia (e.g. living at a high altitude) and that predispose one to chronic lung diseases (e.g. smoking) should be avoided in individuals with SDH genes or MAX mutations." (PMID 31365623, 2019).
diabetes (1 paper, 2020). "Among these are genes associated with insulin (MAX, NUCKS1, PIK3R1, PTPN11), diabetes (PIK3R1) and circadian-related processes (HNRNPU, BHLHE41)." (PMID 34745571, 2020).
dysplasia (1 paper, 2008). A usually neoplastic transformation of the cell, associated with altered architectural tissue patterns. "Progressive overexpression of MYC in the oesophageal metaplasia-dysplasia-adenocarcinoma sequence has been observed previously; prior to this study however, the expression of other members of the MYC/MAX/MAD network had not been studied in any detail in the oesophagus." (PMID 18493233, 2008).
gynecological cancers (1 paper, 2015). "Conclusively, these data lead us to propose the presence of common features among gynecological cancers, other types of cancers, ES cells and the pre-malignant SC junction cells, where the novel E2F/NFY and MAX/CEBP modules play an important role for the pathogenesis of gynecological carcinomas." (PMID 26559525, 2015).
head and neck squamous cell carcinoma (1 paper, 2022). A squamous cell carcinoma that arises from any of the following anatomic sites: lip and oral cavity, nasal cavity, paranasal sinuses, pharynx, larynx, and salivary glands. "MYC/MAX was a hub regulator of LINC00958, which is consistent with the results of studies on head and neck squamous cell carcinoma cells." (PMID 35223488, 2022).
Insulin resistance (1 paper, 2006). Increased resistance towards insulin, that is, diminished effectiveness of insulin in reducing blood glucose levels. "Max interactor protein, MXI1 (gene L07648) competes for MAX thus negatively regulates MYC function and may play a role in insulin resistance." (PMID 17217525, 2006).
laryngeal carcinoma (1 paper, 2022). Carcinoma that arises from the laryngeal epithelium. "Later on, a study published after the date of the annotation files we used to train our models, suggested that MYCT1 synergistically interact with MAX as a co-transcription factor or a component of MAX transcriptional complex, involved in enhanced apoptosis in laryngeal cancer cells." (PMID 35803984, 2022).
liver fibrosis (1 paper, 2021). "MAX conc, MAX slope, and AUC were found to decrease gradually with the development of liver fibrosis." (PMID 33407215, 2021).
mental disorder (1 paper, 2025). A disease that has its basis in the disruption of mental process. "We identified four key genes and their downstream pathways, specifically QDPR, DBI, MAX and HP genes, linking the mental disorders and susceptibility to the development of IBD." (PMID 40118833, 2025). "By integrating evidence from multi-omics perspectives, we identified four mental disorder-related genes: QDPR (Tier 1), DBI (Tier 1), MAX (Tier 3) and HP (Tier 3) as prior regulatory genes in the pathogenic pathway of IBD and its subtypes." (PMID 40118833, 2025). "We identified four mental disorder-related genes, i.e., QDPR, DBI, MAX and HP and their downstream pathways that played crucial role in the susceptibility of IBD and UC, suggesting their potential as intervention and therapeutic targets for gut-brain axis diseases in the future." (PMID 40118833, 2025).
metastatic prostate carcinoma (1 paper, 2017). A carcinoma that arises from the prostate gland and has spread to other anatomic sites. "Data sets with significant down regulation of PrKD1 in metastatic prostate cancer were identified, and the gene expression data for MYC, MAX and MXD1 were compared." (PMID 29108267, 2017).
oesophageal adenocarcinoma (1 paper, 2008). "Elevated expression of c-MYC has been demonstrated in oesophageal adenocarcinoma; however, the expression of other members of the MYC/MAX/MAD network has not been addressed." (PMID 18493233, 2008).
oesophageal cancer (1 paper, 2008). "In conclusion, the expression patterns of c-MYC, MAX and the MAD family were shown to be deregulated in the oesophageal cancer model." (PMID 18493233, 2008).
pancreatic NET (1 paper, 2024). "In addition, eight (7.3%) patients with MAX mutations did not have PCC, but two had ganglioneomas, one had abdominal ganglioneuroblastoma, one had pancreatic NET, one head and neck PGL, and three were asymptomatic carriers." (PMID 39279998, 2024).
pediatric astrocytoma (1 paper, 2016). "We found a mutation on Arg 51 residue to Glu in MAX gene in a patient with bilateral thalamic pediatric astrocytoma in which the primary tumors (left and right thalamus) had nearly identical mutation profiles except for the presence of the MAX R51Q only in one." (PMID 27294413, 2016).
pituitary disease (1 paper, 2022). "A vast amount remains to be learned about PitNET pathogenesis in the setting of SDHx and MAX variants and particularly on the role of pseudohypoxic and kinase signalling pathways in pituitary disease, which may reveal novel biomarkers and medical therapies." (PMID 35938916, 2022).
polydactyly (1 paper, 2024). A disease characterized by the presence of polydactyly, including syndromic and non-syndromic forms. "In summary, we have identified a recurrent germline de novo p.Arg60Gln variant in MAX as a cause of a macrocephaly- and polydactyly-associated syndrome." (PMID 38141607, 2024).